CTLA4 (cytotoxic T-lymphocyte associated protein 4)
Diseases named in the same sentence as CTLA4 in open-access papers (continued):
Sharing a sentence is not in itself a finding about the gene and the disease.
tumor (continued). "In summary, we have observed the best tumor control for SCCVII model in immunocompetent mice studies with APG‐157 and anti‐CTLA‐4 combination treatment." (PMID 38686626, 2024). "In pre-established tumor models, MDNA11 effectively controlled tumor growth when administered as a monotherapy or in combination with anti-PD1 or anti-CTLA4 antibodies." (PMID 39169031, 2024). "We demonstrated the biological functionality of AYA22T-R2-13, confirming its specific binding to CTLA-4 and NKG2A, and its potential to enhance CD8 T cell and NK cell activity, promoting in vitro tumor cell lysis in human cell lines." (PMID 38473398, 2024). "NK/T cell subgroups in HNSCC group highly expressed marker genes of depleted T cells such as CTLA4, LAG3, TIGIT, HAVCR2, etc., indicating that tumor tissue was more sensitive to NK/T cells." (PMID 38582791, 2024). "To assess the potential tumor suppressor role of APOB in HCC, we employed the Spearman correlation coefficient to evaluate the relationship between APOB and CD274, PDCD1, and CTLA4." (PMID 38310202, 2024). "In NSCLC-bearing mouse models, a significant delay in tumor growth was observed with anti-CD47 Ab and anti-CTLA4 therapy alone compared to the control group." (PMID 38398223, 2024). "There are also studies showing that CAR-T cells with blockade of CTLA-4 and LAG-3 exhibit stronger anti-tumor activity in various experimental animal models." (PMID 38571495, 2024). "In contrast, anti-CTLA-4, anti-PD-1, combination anti-CTLA-4 plus anti-PD-1, or neo VAX induced tumor rejection in a majority of mice." (PMID 38187708, 2024). "Approved ICIs like cytotoxic T-lymphocyte antigen-4 (CTLA-4), programmed death-1 (PD-1), its ligand PD-L1, and lymphocyte activation gene-3 (LAG-3) have improved cancer patient outcomes by enhancing anti-tumor responses." (PMID 38375475, 2024). "However, tumour cells may adapt to express CTLA-4, modulating the anti-tumour immune response." (PMID 39001359, 2024). "Immune checkpoint genes, including CTLA4, CD96, and TIGIT, are enriched in the first layer on the tumour side." (PMID 39350478, 2024). "When GITR ligation was combined with CTLA-4-mediated ICI in vitro on HCC-derived TILs, immunosuppression by tumour-derived Tregs was abrogated completely." (PMID 38440738, 2024). "These compounds impaired the CTLA-4/CD80 interaction and inhibited tumor growth in syngeneic and hCTLA-4 mice." (PMID 38312352, 2024). "Lactate promotes CTLA-4 expression in a Foxp3-dependent manner and promotes ubiquitin-specific peptidase 39 (USP39)-mediated RNA splicing in tumor-infiltrating Treg cells." (PMID 39464313, 2024). "On the other hand, their killing effect on the tumor cells at various DOX dose gradients had been likewise noticeably larger compared to those of the FC + LPS-DOX, FC + LPS-DOX+Nb36, FC + LPS-DOX+anti-CTLA-4 mAb and FC + LPS-RGD-Nb36 groups." (PMID 38824143, 2024). "In AML patients experiencing relapse after prolonged post-HSCT remission, functionally impaired CD8+ T cells expressing IRs such as PD-1, CTLA-4, and TIM-3 accumulate in the tumor microenvironment." (PMID 39635535, 2024). "The monocyte can be considered a maestro within the TME in both solid tumors and hematologic malignancies, moreover, the applications of checkpoint inhibitors, such as PD-1, CTLA-4, and BTLA, have emerged as a new upsurge of tumor immunotherapy." (PMID 38742110, 2024). "Similar to PD-1 and CTLA-4, LAG-3 is overexpressed on exhausted T cells within the tumor microenvironment, aiding in cancer cells’ immune evasion." (PMID 39013849, 2024). "Following the same trend, the bispecific antibody ATOR-1015 is also a new generation of bispecific anti-CTLA-4 (IgG1), designed to target the high co-expression of CTLA-4 and OX40 on tumor-infiltrating Tregs." (PMID 39247203, 2024). "After mass development, the mice were systemically administered anti-CTLA4 mAb or anti-PD-L1 mAb, followed by CIRT on one side of the tumor." (PMID 38474078, 2024).
tumor (continued). "It has also been reported that AMPK activator has synergistic anti-tumor effects with anti-PD-1 antibodies, anti-CTLA-4 antibodies, or HMGCR inhibitors in mouse tumor models." (PMID 38762523, 2024). "The combination of this hybrid platform with an anti-CTLA-4 antibody generated significant immune responses and antitumor effects in a B16/BL6 melanoma tumor model." (PMID 37587290, 2024). "Immune checkpoint molecules (ICMs; PD‐1, PD‐L1, CTLA‐4, LAG3), tumor‐infiltrating lymphocytes (TILs; CD8, FOXP3), and other related proteins were evaluated by immunohistochemistry." (PMID 38455493, 2024). "We subcutaneously loaded female C57BL/6J mice with MC38 cells to induce tumor loading and divided the mice into five groups: PBS, TF, anti‐CTLA‐4, anti‐PD‐1, and TF plus anti‐CTLA‐4." (PMID 38938284, 2024). "CTLA-4, LAG3, TIM-3, and PD-1 are the primary co-inhibitory checkpoints involved in tumor development and progression in CRC." (PMID 39839672, 2024). "Anti-CTLA4 treatment has demonstrated efficacy in multiple murine models of GBM, with significant reductions in tumor burden and survival benefits that outperformed anti-PD-1 treatment." (PMID 39409893, 2024). "We measured tumor growth by treating the mice with APG‐157, anti‐PD‐1, and anti‐CTLA‐4 antibody combinations (8 groups)." (PMID 38686626, 2024). "Other studies have shown that CTLA-4 expression is particularly high in MIBC and correlated with tumor size." (PMID 38542078, 2024). "The IPS score, a novel biomarker for tumor response to immunotherapy, is a valuable tool for assessing the efficacy of anti-PD1 and anti-CTLA4 therapies." (PMID 38779664, 2024). "The use of anti-GITR antibodies and anti-CTLA4 antibodies in MethA and CT26 tumor models resulted in increased levels of Teff and IFNγ." (PMID 39329710, 2024). "The addition of anti-CD96 in combination with anti-PD-1, anti-CTLA-4, anti-TIGIT, or doxorubicin chemotherapy resulted in superior antitumor responses by enhancing T-cell activity and suppressing tumor growth." (PMID 38732242, 2024). "Then we used Loupe Browser 7.0 to group spots with gene characteristics (log2 count > 0) of CD68 or CD4 with CTLA4 as THC, and spots with gene characteristics of CD3D or CD3E or CD3G as tumor immune cells." (PMID 39499374, 2024). "When Ipatasertib and anti‐PD1 therapies were combined, both the tumour volume and mass exhibited a notable reduction, while the expression of CD45+CD8+ T cells increased, and that of CD45+CD4+CTLA4+ and CD45+CD4+PD1+ T cells decreased." (PMID 39556022, 2024). "As expected, hot tumor regions displayed markedly higher anti-PD1 favor scores, higher expression, and lower methylation for genes CD274 and CTLA4." (PMID 38803565, 2024). "At the same time, the reduction in tumor Treg prevents the downregulation of costimulatory B7-family proteins (CD80 and CD86) on cDC in a CTLA-4-dependent manner." (PMID 39470607, 2024). "The marked increase in CTLA4 expression in activated CUL5 KO CD8+ T cells, on the other hand, should suppress CUL5 KO CD8+ T cells by B7-expressing cells in tumor." (PMID 38242867, 2024). "An ongoing phase 1 study (NCT04572152) is evaluating the safety, anti-tumour activity and pharmacokinetics of AK119 in combination with an anti-PD-1/CTLA-4 bispecific antibody in advanced solid tumours." (PMID 38660136, 2024). "Tregs, known for their highly suppressive and hyperproliferative features in the TME, express heightened levels of CD25, CTLA4, GITR, OX40, ICOS, and neuropilin-1 and accumulate significantly during tumor development." (PMID 38787791, 2024). "Although statistically not significant, there was a trend toward increase in the population of tumor neutrophil and decrease in NKT population for APG‐157 and anti‐CTLA‐4 combination." (PMID 38686626, 2024).
tumor (continued). "Research in both animal models and human cancer patients has shown that blocking CTLA-4 with monoclonal antibodies improves the effector activity of CD4 +and CD8 +T cells, which is important for anti-tumor immunity." (PMID 39127974, 2024). "In these tumors, an anti-tumor immune response appears to have been initiated, but then inhibited (presumably by upregulation of T cell inhibitory receptors like PD1 and CTLA-4), that was then “unleashed” by checkpoint blockade." (PMID 39199568, 2024). "Studies have shown that using HDAC inhibitors like belinostat and trichostatin A (TSA) in combination with anti-CTLA-4 therapy can reduce the number of Tregs and increase the production of IFN-γ by tumor-reactive CD8+ T cells in the TME." (PMID 38473997, 2024). "Preclinical studies have demonstrated that dual blockade of PD-1 and CTLA-4, combined with the GM-CSF gene-transfected GVAX vaccine, effectively induced tumor rejection and restored T-cell activity in CRC murine models." (PMID 39877377, 2024). "We found that it was correlated with tumor immunotherapy targets BTLA, CTLA4, HAVCR2, LAG3, PDCD1, and TIGIT in HNSC; ICOS were all significantly correlated." (PMID 39483471, 2024). "In vivo studies have demonstrated that OS patients exhibit enhanced anti-tumor activity of cytotoxic T cells following treatment with CTLA-4 antibodies, revealing the potential of CTLA-4 inhibitors in the treatment of OS." (PMID 38280005, 2024). "At present, PD‐1/PD‐L1 inhibitors plus CTLA‐4 inhibitors are the most widely used ICI therapies, as they can restore T‐cell activity of killing tumor cells." (PMID 39001676, 2024). "Our results confirm that most immune checkpoints (such as CTLA-4 and PDCD1) in the C3 subtype (βAMRGs-active) exhibit low expression levels, implying an augmented anti-tumor immune response." (PMID 38637116, 2024). "Even though, monoclonal antibody against CTLA-4, such as ipilimumab and tremelimumab would be a therapeutic option since we observed an upregulation of CTLA-4 expression in the tumor." (PMID 38228856, 2024). "The combined anti-CTLA-4 and anti-PD-L1 antibodies activate and increase CD8+ T cells to enter the tumor and decrease Tregs and MDSCs." (PMID 38893154, 2024). "The research utilized a subcutaneous transplantation tumor model of NSCLC in mice, observing significant anti-tumor effects with the combination therapy targeting CD47 and CTLA4." (PMID 38398223, 2024). "CTLA4, an important immune checkpoint blocker (ICB), is primarily expressed in immune cells, but has also been found in tumor cells." (PMID 38398223, 2024). "Whole-transcriptome RNA analysis found that the cold nodule demonstrated lower expression of genes related to antigen presentation (HLA) and, paradoxically, classical tumor immune tolerance markers such as PD-L1 (CD274) and CTLA-4." (PMID 38253539, 2024). "CTLA-4 binds to APC receptors CD80/CD86, reduces T cell activation and proliferation at GBM tumor site." (PMID 38778925, 2024). "We performed qRT-PCR analysis on MB49 and B16F10 tumor tissues harvested from mice that were systemically treated with either EC5026, ICIs (anti-PD-1 or anti-CTLA4), a combination of EC5026 and ICIs, or vehicle as detailed above." (PMID 38330013, 2024). "Expression and interaction of CTLA-4 and the TME are thought to correlate with the stage of CHL, as they can reflect the extent of immune evasion by the tumour." (PMID 38978137, 2024). "Mice received intraperitoneal (i.p.)injections of 0.5 mg clodronate every 3 days, starting from the day of tumor injection (day 0), in addition to CTLA-4 blockade monotherapy or combination therapy of IVAX and CTLA-4 blockade." (PMID 38517331, 2024). "Immunosuppressive molecules, such as PD‐L1, CTLA‐4, TIM‐3, BTLA, CD160, LAG3, and 2B4,73 not only dampen the tumor's immune response but also impact the efficacy of OVs in infecting tumor cells." (PMID 39399642, 2024).
tumor (continued). "Recently, the comprehensive treatment of advanced tumours increasingly relies on immune checkpoint blockade (ICB) drugs targeting PD‐1/PD‐L1 and CTLA‐4." (PMID 39602465, 2024). "Tumor-infiltrating Tregs (TI-Tregs) receive TCR signals from cDCs and downregulate CD80/CD86 expression on cDCs via CTLA-4, thereby inhibiting T cell activation and expansion." (PMID 39290699, 2024). "LAG3+ T cells highly expressed LAG3 and CTLA4+ T cells highly expressed CTLA4 and TIGIT, which were also higher in tumor tissues than in normal tissues." (PMID 38604154, 2024). "These humanized monoclonal antibodies target inhibitory receptors (CTLA-4, PD-1, LAG-3, TIM-3) or ligands (PD-L1) expressed on T lymphocytes, antigen presenting cells, and tumor cells and elicit an anti-tumor response by stimulating the immune system." (PMID 40757683, 2024). "Next, we focused on Y1.7LI and delayed treatment initiation until day 7 post-transplant, a time point at which anti-CTLA-4, anti-PD-1, anti-CTLA-4 plus anti-PD-1, or neoAg SLP vax still induced tumor rejection in a majority of mice." (PMID 39446585, 2024). "It has been demonstrated that hypoxia alters the levels of immune checkpoints like CTLA-4, PD-1/L-1, CD47, and TIM3 to modify the immune cell-induced anti-tumor response, thus suppressing immune surveillance." (PMID 38165484, 2024). "For example, Tregs (regulatory T cells) suppress immune response by expressing molecules like CTLA-4 and TGF-β, facilitating tumor cell escape." (PMID 39539544, 2024). "In this study, a mouse tumor model Hepa1-6, which is sensitive to CD4+ T cell activity, was used to conduct mechanistic analysis of an anti-CTLA-4 Ab." (PMID 39106430, 2024). "This treatment regimen, which involves an Fc-enhanced anti-CTLA-4 antibody (BOT) and an anti-PD-1 antibody (BAL), led to an unusual “inside-out” (serosa-to-mucosa) pattern of tumor regression." (PMID 38790167, 2024). "This approach helps in silencing CTLA-4 and PD-1 genes, resulting in the upregulation of CD8 T cells by creating a pro-immune modulatory tumor environment, gearing the ability of T cells towards tumor recognition." (PMID 38751938, 2024). "Mouse cohorts of metastatic CRC were treated with the TGF-βR inhibitor combined with KN046, which blocks programmed death ligand 1 (PD-L1) and CTLA-4, followed by 68Ga-FAPI and 18F-FDG micro-PET/CT imaging to assess tumor responses." (PMID 38175716, 2024). "Mice received either anti-PD-1, anti-CTLA-4 or/and MerTK ASO starting from day 1 post tumor implantation." (PMID 38443968, 2024). "Immune checkpoint molecules such as PD-L1, CTLA-4, and CD47 were identified as key players in tumor immune evasion, contributing to tumor growth and metastasis." (PMID 39539964, 2024). "By targeting immune checkpoints with anti-PD-1, anti-PD-L1, anti-CTLA4, and, more recently, anti-LAG-3 agents, ICIs disinhibit the immune system to unleash anti-tumor immune responses." (PMID 38254829, 2024). "As another strategy, combination of anti-CTLA4 therapy and TU2218 resulted in high complete regression (CR) rates in CT26 and WEHI-164 tumor models." (PMID 39105882, 2024). "Third, the correlation module results showed that DSN1 was related to some well-known tumor immune-related biomarkers, such as PDCD1, CD274, PDCD1LG2, and CTLA4." (PMID 39555702, 2024). "Trans-artery/intra-tumor infusion of PD1/PDL1 antibody and/or CTLA4 antibody ipilimumab plus chemotherapeutic drug and comparison of their differences." (PMID 39273502, 2024). "Contrasting expectations, pTc HROC113 recognized tumor cells better after control culture than after ICI-supplemented co-culture, showing significantly deterioration after co-culture with PD-1 or CTLA-4 supplementation (p = 0.048 and p = 0.041, respectively)." (PMID 39075115, 2024).
tumor (continued). "While comparing between matched and unmatched tumour and normal tissue samples, upregulation of checkpoint receptor genes, notably CD47, CTLA4, HAVCR2, PVRIG, SIGLEC7, and SIGLEC9, were specifically detected in malignant compared to normal tissues." (PMID 39877370, 2024). "Compared to sham control mice, the CD45hi/CD11bhi compartment significantly expands in tumor-bearing mice and exhibits a myeloid-specific signature composed of VISTA, CD80, PD-L1, CTLA-4, MHCII, CD40, and CD68." (PMID 39123357, 2024). "Some moderate responders benefit from combination of anti-CTLA4 with anti-PD1, which is evident from better cytotoxic T-cell: T-regulatory cell ratio and enhancement of tumor cytotoxicity." (PMID 38383563, 2024). "Overwhelming evidence indicates that the combination of PD1 with HAVCR2, CTLA4 or TIGIT inhibitors can more effectively improve T-cell function and eliminate tumour cells." (PMID 38297380, 2024). "In the tumor microenvironment of patients with T-ALL/T-LBL, the immunosuppressive components TIGIT and CTLA4 show reduced expression." (PMID 38464517, 2024). "demonstrate that administering DAT to mice leads to a deceleration in tumor development and amplifies the efficacy of ICI immunotherapy, particularly when combined with anti-CTLA-4 or anti-PD-1 treatments." (PMID 39351241, 2024). "PD-1 blockade has been shown to reinvigorate and expand exhausted tumor-reactive PD-1+ CD8 T cells and CTLA-4 blockade to promote T cell priming, clonal expansion, and CD4 and CD8 T cell trafficking into immunologically cold tumors." (PMID 39190534, 2024). "Immune checkpoint inhibitors, including anti-CTLA4 and anti-PD-1, restore the immune system by “removing the brake”, promoting CD8-positive T-cells anti-cancer activity, enabling tumor regression and long-term cancer control in up to 50% of patients." (PMID 38791968, 2024). "We further showed that both CpG-Stat3 siRNA and CTLA4 antibody inhibit STAT3 in B malignant cells, leading to tumor cell apoptosis and/or growth inhibition." (PMID 39618825, 2024). "On the other hand, CD4 + and CD8 + T cells trigger tumour escape by expressing immune checkpoint molecules (PD-1, LAG-3, CTLA-4, TIM-3) that bind to their related ligands on DCs and/or tumours, thereby stopping an immune reaction." (PMID 39720956, 2024). "In consideration of M2 macrophages and Treg cells exhaust CD8+T cells in tumor immune microenvironment (TIME), we explored the correlation between several immune checkpoints expression (PD-1, TIM-3, CTLA-4, LAG3 and TIGIT) and TIBs in the TCGA database." (PMID 38762825, 2024). "Another study combined CTLA-4 inhibitors with targeted therapies against the IGF signaling pathway, resulting in enhanced tumor regression and reduced metastatic spread." (PMID 39896817, 2024). "In lymphocyte-depleted cancer, PD-1 and CTLA-4 blockade promote radiotherapy-induced Treg responses in a CD86-dependent manner and prevent CD8+ T-cell mediated tumor control." (PMID 38349740, 2024). "Presently, only two anti-CTLA-4 human monoclonal antibodies (Ipilimumab and Tremelimumab) are FDA-approved for use, either alone or in combination therapies, enhancing anti-tumor effects and prognosis." (PMID 38473398, 2024). "The inhibitory activity of Tregs, through cell–cell contact with immune cells occurs mainly via the co-inhibitory receptors, including CTLA4 and PD1, which have been targeted clinically to improve anti-tumor T-cell responses." (PMID 39264416, 2024). "Immunotherapy, notably immune checkpoint inhibitors targeting PD‐1 and CTLA‐4, has revolutionized the treatment paradigm of SKCM by augmenting anti‐tumor immunity and improving patient outcomes." (PMID 38766879, 2024). "CTLA-4 (CD152) is predominantly expressed on the surface of activated T cells as well as in regulatory T cells (Tregs) and PD-1+ CD4+/CD8+ tumor-infiltrating lymphocytes (TILs)." (PMID 38627681, 2024).